BDNF (brain derived neurotrophic factor)
Diseases named in the same sentence as BDNF in open-access papers (continued):
Sharing a sentence is not in itself a finding about the gene and the disease.
depression (continued). "A six-hr hypothermia treatment applied 45 min after stroke prevented depression and anxiety like behaviors examined at 6 weeks after stroke, as well as restored BDNF expression and oxytocin signaling." (PMID 32010477, 2020). "A few studies have shown that serum brain-derived neurotrophic factor (BDNF)level in post-stroke depression is highly correlated with memory andneuropsychiatric disturbances." (PMID 32206197, 2020). "Reduction of BDNF in the brain has been proposed as a candidate for possible involvement in depression." (PMID 32952549, 2020). "This study found that one of the target genes of miR-16 is brain-derived neurotrophic factor (BDNF) and that the upregulation of miR-16 was accompanied by the downregulation of BDNF in the depression model of rats." (PMID 32774683, 2020). "A growing evidence has suggested that neurotrophin, and especially brain-derived neurotrophic factor (BDNF), is important in anxiety and depression." (PMID 32210759, 2020). "Further studies are needed to explore the mechanism of action of oleuropein on different pathways involved in depression, such as BDNF and inflammatory pathway." (PMID 32094406, 2020). "In a sleep deprivation-induced depression mouse model, exercise was also found to normalize the decreased levels of BDNF, and therefore exert neuroprotective effect and neurotrophic effect." (PMID 33329133, 2020). "Intriguingly, monocytes had also the lowest CpG methylation at the CREB binding site—a motif repeatedly shown to be involved in depression by mediating several effects down- and upstream of BDNF." (PMID 32636772, 2020). "It appeared that the actions of a chronic stressor regimen on hippocampal BDNF were more pronounced in females than in males, which is in keeping with the greater depression vulnerability in human females." (PMID 33408619, 2020). "Similar behaviors were found in BDNF +/met knock-in mice that exhibited depression- and anxiety-like behaviors, and impaired working memory after stress exposure." (PMID 32793001, 2020). "BDNF is related to the survival, growth, and differentiation of neurons, and plays an important role in the signal transduction of depression." (PMID 33658934, 2020). "In the past, lower serum BDNF levels in patients suffering from a number of neurological conditions compared to HC have been reported (such as depression, schizophrenia, Alzheimer’s,39, 40 or Huntington’s disease." (PMID 33031634, 2020). "There are gender differences as well as BDNF expression differences in patients with cardiovascular disease and depression." (PMID 33353544, 2020). "BDNF modulates survival of neurons and plasticity mechanisms in learning and memory and plays an important role in the pathogenesis of depression." (PMID 32843073, 2020). "Compared with preacupuncture treatment conditions, depression-like behaviours were ameliorated and induced an increase in BDNF expression in the hippocampus after treatment." (PMID 33029119, 2020). "Spearman’s rank correlation test was applied to find the correlation between serum BDNF levels and the severity of depression." (PMID 32085720, 2020). "BDNF are involved in the pathogenesis of depression, with decreased growth and survival of neurons, and thus possibly leads to gray matter atrophy shown on magnetic resonance imaging." (PMID 32952549, 2020). "For example, one study found the hypermethylation of BDNF promoter in the peripheral blood cells was correlated with the severity of the depression." (PMID 33101076, 2020). "In contrast, we found increased BDNF-TrkB signaling in the NAc from rats with anhedonia-like phenotypes, consistent with the previous reports from rodents with depression-like phenotypes." (PMID 29882089, 2020). "Later studies showed that proBDNF exerted a function opposite that of BDNF in such CNS diseases as depression and Alzheimer’s." (PMID 32466783, 2020).
depression (continued). "The experimental models showed that docosahexaenoic acid (DHA) supplementation directly correlated with the BDNF level in traumatic brain injury, depression, and age-related decline in cognitive function." (PMID 33343231, 2020). "Serum BDNF levels decreased in patients with major depression and increased after symptoms were relieved due to treatment with antidepressants." (PMID 32733578, 2020). "The expression of BDNF was significantly elevated in animal models of depression-like behavior after undergoing ECS." (PMID 32153449, 2020). "For example, rats with low-novelty-seeking behavior are resistant to induction of depression-like behaviors after social defeat stress, which is correlated with the upregulation of BDNF in the hippocampus." (PMID 32085670, 2020). "It is well known that high levels of endogenous neurotrophins, BDNF and GDNF, in the brain and peripheral blood reduce the hippocampus gray matter loss, improve memory, and reduce the occurrence of depression in the elderly (see section “Introduction”)." (PMID 33192480, 2020). "Chronic insomnia has been associated with changes in cortisol and serum brain-derived neurotrophic factor (BDNF) levels, which in turn are also changed in major depression." (PMID 32410966, 2020). "In major depression, there exists a clear relationship between BDNF levels and the depressive state, as well as the success of antidepressant therapy." (PMID 32116853, 2020). "BDNF was also suggested to play a crucial role in the pathophysiology of obesity and metabolic syndrome in neurodegenerative disorder such as depression because low plasma levels of BDNF were reported in patients with metabolic syndrome." (PMID 32115672, 2020). "BDNF has been widely investigated with respect to major depressive disorder as well as bipolar disorder." (PMID 32116853, 2020). "BDNF is one of the most characterized neurotrophins, whose serum and hippocampal expression levels decrease under stress or depression, while exercise significantly increased BDNF expression that lasted for 1–2 weeks after exercise intervention." (PMID 32774242, 2020). "Multiple reports and meta-analyses have shown that patients with depression have lower blood BDNF levels." (PMID 32351365, 2020). "We found that CORT injection promoted depression-like behavior and significantly decreased BDNF and TrkB expression in the hippocampus." (PMID 33265983, 2020). "Our findings reveal that PEA exerts antidepressant effects by modulating the BDNF/TrkB/CREB signaling pathway in a mouse model of CORT-induced depression." (PMID 33265983, 2020). "Another clinical study found similar changes of BDNF hypermethylation in the buccal tissue of depression patients." (PMID 33101076, 2020). "Given that another study showed that knockdown of BDNF in the dentate gyrus induces depression-like effects in rats, the role of BDNF in depression needs further investigation at molecular cellular levels." (PMID 32492978, 2020). "Among neurotrophins, brain-derived neurotrophic factor (BDNF) has a leading role in the pathophysiology of depression." (PMID 32849818, 2020). "Clinical trials showed that Mediterranean diet is correlated with low incidence of depression, and high level of brain derived neurotrophic factor." (PMID 32094406, 2020). "Serum BDNF concentration < 5.86 ng/ml within 24 h after stroke onset is predictive for the danger of post-stroke depression development." (PMID 31701356, 2020). "Stress, which is a major contributor to depression, reduces BDNF expression and serum BDNF levels are lower in depressed patients." (PMID 33109198, 2020). "We reviewed recent publications related to acupuncture on related miRNAs and BDNF in neurodegenerative diseases and depression." (PMID 33029119, 2020). "In the hippocampus they have an antidepressant effect, whereas in the ventral tegmental area and nucleus accumbens, BDNF produces a depression-like effect." (PMID 33255237, 2020).
depression (continued). "Activation of the pro-BDNF p75NTR receptor reduces neuroplasticity and facilitates long-term depression." (PMID 32218234, 2020). "Increased free radical concentration and oxidative stress are directly proportional to low concentrations of BDNF and promote depression and anxiety." (PMID 33014278, 2020). "A large number of studies showed neurotrophic factors, especially BDNF showed a close relationship with depression." (PMID 32351365, 2020). "BDNF is a neurotrophin expressed in the hippocampus and is involved in processes related to memory and learning and is thought to play a crucial role in major depression." (PMID 32824367, 2020). "Many studies have shown that BDNF is closely related to depression and that BDNF mediates neurogenesis and synaptic plasticity." (PMID 33029119, 2020). "Oral infection with P. gingivalis in mice can produce an impairment of learning and memory abilities by the release of pro-inflammatory cytokines in the brain, as well as depression-like behavior and a reduction of brain-derived neurotrophic factor (BDNF )." (PMID 31906991, 2020). "Studies are still needed to elucidate the role of BDNF and DA in the comorbidity of addiction and depression." (PMID 32694984, 2020). "The neurotrophin BDNF is considered a link between the antidepressant drug and the neuroplastic changes, resulting in the improvement of depression." (PMID 33331415, 2020). "Recent studies have suggested that both BDNF and another protein-mammalian target of rapamycin (mTOR) have important roles to play in the development of some mental diseases such as depression and anxiety." (PMID 32198387, 2020). "Recent data demonstrate that miR-124-mediated post-transcriptional regulation of CREB1 and BDNF can improve depression-like behavior in a rat model." (PMID 33096634, 2020). "In in vitro and in vivo models of depression, BDNF was shown to improve depressive-like behavior by upregulating anti-inflammatory cytokine IL-10, IL-4, and TGF-β1 and downregulating the pro-inflammatory cytokine IL-1β, IL-17, and TNF-α." (PMID 32256638, 2020). "Transcriptional repression of the critical brain-derived neurotrophic factor (Bdnf) has been reported in C57BL/6 mice exhibiting depression-like phenotype following chronic social defeat stress (CSDS)." (PMID 33182385, 2020). "Convincing evidence supports the view that BDNF plays an important role in the pathogenesis of depression and diabetes." (PMID 33568996, 2020). "BDNF in the hippocampus plays a key role in chronic unpredictable mild stress (CUMS)-induced depression-like behaviors and alterations in dendritic spines in hippocampal pyramidal neurons." (PMID 33265983, 2020). "Regarding depression, we observed positive correlations between brain-derived neurotrophic factor (BDNF) and the Lachnospiraceae family (Lachnospiraceae_uc and Murimonas) before flavonoid orange juice treatment." (PMID 32570775, 2020). "Regardless, based on the works from Dr Benoliel's group, there is a clear-cut association between lower levels of hippocampal and circulating BDNF and vulnerability to depression after SD due to local oxidative stress." (PMID 33344701, 2020). "In this review, we introduce the various changes in hippocampal plasticity in depression and discuss the role of BDNF and CR in the treatment of depression." (PMID 33293948, 2020). "It has been well demonstrated that CRTC1, BDNF and neurogenesis play critical roles in not only depression but also many other neurological disorders, such as Alzheimer's disease, Parkinson's disease, stroke and epilepsy." (PMID 33519490, 2020). "That indicates that inflammation affects the expression of BDNF, which contributes to the effect of inflammation on the development of depression." (PMID 32513185, 2020). "In our previous study, we observed a reduction in the relative abundance of Clostridium XIVb in patients with major depressive disorder, which correlated negatively with the serum BDNF levels." (PMID 33391265, 2020).
depression (continued). "Recent clinical studies have shown that BDNF is a promising biomarker, and BDNF levels in serum of patients with depression are significantly reduced, while antidepressant treatment reverses this effect." (PMID 32185198, 2020). "Treatment with Dammarane Sapogenins improved BDNF expression in the hippocampus and prefrontal cortex, and reduced anxiety-like and depression-like behaviour in mice." (PMID 33344701, 2020). "A series of studies have revealed the important role of the BDNF-ERK-CREB signaling pathway in depression-like behavior and antidepressant effects." (PMID 32185198, 2020). "In particular, reductions in serum and plasma BDNF have been found in patients affected by depression, and in those who committed suicide." (PMID 33066277, 2020). "In the same research, by examining human postmortem brain samples, they also found a positive correlation between BDNF levels in the NAc and depression, highlighting the clinical relevance of this social defeat model to neurotrophin and mental disorders." (PMID 32085670, 2020). "Rg1 also regulates BDNF expression and attenuates depression-like behaviors induced by chronic stress, and Rg3 and Rg5 similarly exhibit antidepressant-like effects in mice by activating hippocampal BDNF signaling." (PMID 32570881, 2020). "CREB is a transcription factor, and its interaction with BDNF has a critical role in the altered neuroplasticity observed in major depression." (PMID 33051451, 2020). "Decreased BDNF concentrations in depression normalize in response to pharmacological treatment and ECT." (PMID 33255237, 2020). "It is observed that the BDNF/ERK/CREB neurotrophic signaling pathway plays an important role in the improvement of depression-like behavior." (PMID 32982748, 2020). "A decreased level of BDNF in the brain, particularly the hippocampus, is a well-known symptom of depression, clinically and pre-clinically." (PMID 33322645, 2020). "Depression scores were significantly (P = 0.03) decreases and BDNF levels significantly (P = 0.04) increased in the DM30 + MM5 group than in the Placebo group." (PMID 32115672, 2020). "Among all neurotrophic factors, BDNF is the best-studied in depression, which exerts its effects through two specific receptors, tyrosine kinase receptor (Trk)B and p75." (PMID 32150824, 2020). "BDNF has been shown to play a role in antidepressant treatments in major depressive disorder (MDD) and also has an effect in generalized anxiety disorder (GAD)." (PMID 32655658, 2020). "This study provides novel evidence that the increase in neurotrophins plasma levels, including BDNF and NT-4, is correlated with the occurrence of depression and anxiety during long-term recovery after METH abstinence." (PMID 32210759, 2020). "Several lines of evidence suggest that BDNF is involved in depression and plays an important role in the maintenance and survival of neurons and in synaptic plasticity." (PMID 32942585, 2020). "Most studies on depression reported reduced serum and plasma BDNF levels in depressed patients, compared with controls." (PMID 32517269, 2020). "Nonetheless, it is still unclear to what extent PTSD can attribute to the lower levels of measured BDNF in the presence of depression and SSRI intake." (PMID 33152026, 2020). "A study also found decreased hippocampal levels of brain-derived neurotrophic factor (BDNF) in a preclinical model of depression, and these were normalized by vitamin D administration." (PMID 32102680, 2020). "Despite the well-known contradictions of the research results, an important role of BDNF in the pathogenesis of depression and the development of both rapid and delayed antidepressant actions has been established." (PMID 32992988, 2020). "Remarkably, according to the published literature, AD, stroke, and PD are usually accompanied by depression, and these neurodegenerative diseases and depression are related to BDNF." (PMID 33029119, 2020).
depression (continued). "The variable with thestrongest correlation with post-stroke depression was 8-OhdG, followed by BDNF, andMDA." (PMID 32206197, 2020). "Based on the current analysis of the published literature, we summarize that acupuncture treatment seemingly restores the level of BDNF, which is thought to play significant roles in depression and neurodegenerative diseases such as AD, stroke, and PD." (PMID 33029119, 2020). "A significant decrease of BDNF levels has been demonstrated in animal models of depression stress-induced as well as in depressed patients." (PMID 32435223, 2020). "Brain BDNF levels have been found to be reduced in animals and patients with depression, as well as postmortem samples of subjects with depression." (PMID 32513185, 2020). "CYDXF (at dose of both 2.73 and 5.46 g/kg) attenuated chronic stress-induced abnormal ovarian follicular development by relieving depression-like behaviors and improving ovarian function through partly the regulation of the BDNF-mediated PI3K/Akt pathway." (PMID 32265693, 2020). "Our results, which are consistent with previous studies, suggest that BDNF and NT-4 are correlated with psychiatric symptoms such as depression and anxiety." (PMID 32210759, 2020). "In contrast, AE upregulated phosphorylation of AMPAR receptor and brain-derived neurotrophic factor (BDNF) hippocampus in CUMS depression rats." (PMID 33374661, 2020). "It has been found that the expression of BDNF in the pre‐frontal cortex and hippocampus was downregulated in animal depression models, so as the level of BDNF in depressed patients." (PMID 32266752, 2020). "Bacopaside I is also reported to enhance the BDNF signaling pathway in a mouse model of depression, at least in part via activation of pERK/pCREB/BDNF signaling involved in the neurotrophic activity and neurogenesis." (PMID 32397562, 2020). "Further research is needed that includes pre-menopausal women to compare the effects of NW and NW with RSA training on BDNF and GDNF levels, as well as on cognitive function, risk of depression, and cardiopulmonary efficiency." (PMID 33192480, 2020). "In agreement with the decreased levels of BDNF under depression conditions, the platelet BDNF content is significantly reduced in patients with depression compared to control subjects, and the antidepressant pharmacotherapy normalize its levels." (PMID 33066277, 2020). "Experimentally, a hypercaloric diet reduces hippocampal brain-derived neurotrophic factor (BDNF) resulting in the development of depression–anxiety like behaviors in young rats." (PMID 33333828, 2020). "The polymorphisms in two such genes, the BDNF and SLC1A3, have been reported to be linked with either depression/stress or with suicidal behaviour." (PMID 32171272, 2020). "To confirm the effect of BTS treatment on our reserpine-induced depression model, we observed BDNF and p-CREB expression in the hippocampus using immunofluorescence." (PMID 32754030, 2020). "Most interestingly, numerous studies have shown that EA can not only inhibit the expression of miR-16 in the hippocampus but also increase the levels of BDNF in the brains of depression model rats." (PMID 33029119, 2020). "Venlafaxine also inhibits hippocampal neuron apoptosis in depression by upregulating the expression of BDNF in the hippocampus of rats." (PMID 33293948, 2020). "A second important candidate gene is BDNF (brain-derived neurotrophic factor; located on chromosome 11p13) whose molecular pathology has been extensively studied in depression cases." (PMID 32171272, 2020). "This suggests a potential transdiagnostic mechanism of low BDNF-related anhedonia in AUD depression co-morbidity." (PMID 32372985, 2020). "BDNF levels in patients with major depression after therapy are still controversial and the short follow-up of most studies is a limiting factor." (PMID 32508690, 2020).